PTDSS1 (phosphatidylserine synthase 1)
Description:
Catalyzes a base-exchange reaction in which the polar head group of phosphatidylethanolamine (PE) or phosphatidylcholine (PC) is replaced by L-serine. Catalyzes mainly the conversion of phosphatidylcholine. Also converts, in vitro and to a lesser extent, phosphatidylethanolamine.
Synonyms: KIAA0024; PSSA; PSS1; LMHD
Tractability: Small molecule: a structure with a bound ligand is known. Antibody: UniProt predicts a signal peptide or a membrane-spanning region. PROTAC: ubiquitination databases record sites on it; its protein half-life has been measured.
Target class: Enzyme; Transferase
Gene: Protein-coding gene on chromosome 8 (96,261,902 to 96,336,995, forward strand). Ensembl gene ENSG00000156471.
Subcellular location: Endoplasmic reticulum membrane
Subcellular location (Human Protein Atlas): Endoplasmic reticulum; Nucleoplasm
Pathways (Reactome):
Metabolism: Synthesis of PS
Gene Ontology:
Molecular function: L-serine-phosphatidylcholine phosphatidyltransferase activity; L-serine-phosphatidylethanolamine phosphatidyltransferase activity; transferase activity
Biological process: phosphatidylserine biosynthetic process
Cellular component: membrane; endoplasmic reticulum membrane
Genetic constraint (gnomAD): Loss-of-function variants: 41 observed, 68.52 expected, observed/expected ratio (o/e) 0.6, 90% interval 0.47 to 0.78. The upper end of that interval is the gene's LOEUF score, 0.78, which puts it in group 3 of 6, group 1 being the genes least tolerant of losing a copy. Missense variants: 392 observed, 586.53 expected, observed/expected ratio (o/e) 0.67, 90% interval 0.61 to 0.73. Synonymous variants: 182 observed, 206 expected, observed/expected ratio (o/e) 0.88, 90% interval 0.78 to 1.
Homologues: Orthologues: chimpanzee PTDSS1 (100% identical), macaque PTDSS1 (99% identical), pig PTDSS1 (98% identical), mouse Ptdss1 (97% identical), dog PTDSS1 (97% identical), rat Ptdss1 (94% identical), tropical clawed frog ptdss1 (86% identical), guinea pig PTDSS1 (82% identical), zebrafish ptdss1a (78% identical), rabbit PTDSS1 (77% identical), zebrafish ptdss1b (77% identical), Drosophila melanogaster Pss (49% identical). Paralogues in human: PTDSS2 (30% identical).
Diseases named in the same sentence as PTDSS1 in open-access papers:
PTDSS1 is named in the same sentence as 32 diseases in open-access papers, as found by Europe PMC text mining. Sharing a sentence is not in itself a finding about the gene and the disease. The quoted sentences say what the papers report.
Lenz-Majewski syndrome (6 papers, 2018 to 2025). "There are many studies about relationship between the mutation in the PTDSS1 gene and Lenz-Majewski syndrome." (PMID 37489460, 2023). "Pathogenic variants in the phosphatidylserine synthase 1 gene (PTDSS1) cause Lenz-Majewski syndrome (MIM #151050), characterized by craniofacial, dental, and limb abnormalities." (PMID 30779713, 2019). "This disorder called Lenz–Majewski syndrome (LMS) is associated with gain of function mutations in PTDSS1, encoding an enzyme involved in phospholipid biosynthesis." (PMID 29341480, 2018). "Lenz-Majewski syndrome (LMS) is an ultra-rare congenital disorder with progressive skeletal dysplasia, cutis laxa, and intellectual disability, typically caused by pathogenic variants in the PTDSS1 gene." (PMID 40837678, 2025).
breast carcinoma (3 papers, 2023 to 2025). "PTDSS1 is frequently amplified (>20%) in a variety of cancer types, including bladder cancer, breast cancer, head and neck cancer, and melanoma." (PMID 40929270, 2025). "Consistent with that, PTDSS1 expression is negatively correlated with the survival of patients with breast carcinoma." (PMID 38048228, 2024).
Intellectual disability (3 papers, 2019 to 2025). "Indeed, gain-of-function pathogenic variants in PTDSS1 coding PS synthase cause sclerosing bone dysplasia and intellectual disability (Lens-Majewski syndrome; OMIM # 151050), and pathogenic variants in PISD1 coding PS decarboxylase cause Spondyloepimetaphyseal dysplasias." (PMID 34489854, 2021).
lung carcinoma (3 papers, 2020 to 2024). "PTDSS1-KO SU-DHL-6 lymphoma, but not A549 lung carcinoma, also showed significant cell death." (PMID 38048228, 2024).
autism (2 papers, 2016 to 2023). Persistent deficits in social interaction and communication and interaction as well as a markedly restricted repertoire of activity and interest as well as repetitive patterns of behavior. "The novel potential autism susceptibility genes PTDSS1 and AREG were uncovered and warrant further genetic and functional analyses." (PMID 26742492, 2016).
dwarfism (2 papers, 2021 to 2022). "Gain‐of‐function mutations in the phosphatidylserine synthase 1 (PTDSS1) gene cause Lenz‐Majewski hyperostotic dwarfism and developed a severe skeletal dysplasia." (PMID 33664783, 2021). "These genes were mainly involved in bone resorption (e.g., PTGER4), bone mineralization (e.g., BMP6), and dwarfism (e.g., GDF6 and PTDSS1)." (PMID 34893856, 2022).
B cell lymphomas (1 paper, 2024). "Inhibition of PTDSS1 in B cell lymphoma cells caused a reduction of PS and phosphatidylethanolamine levels and an increase of phosphoinositide levels." (PMID 38048228, 2024). "Using a recently developed PTDSS1 inhibitor, we screened 47 cancer cell lines for survivability under the restriction of PS synthesis and identified B cell lymphoma as a highly PS-dependent cancer type." (PMID 38048228, 2024). "We screened 47 cancer cell lines for survival dependency on phosphatidylserine (PS) synthesis using a PS synthase 1 (PTDSS1) inhibitor and found that B cell lymphoma is highly dependent on PS." (PMID 38048228, 2024). "Our screen revealed that B cell lymphoma is highly dependent on PTDSS1 despite intact PTDSS2 expression." (PMID 38048228, 2024). "Therefore, alterations not only of PIPs but also of PE potentially contribute to the cytotoxicity of PTDSS1 inhibition in B cell lymphoma." (PMID 38048228, 2024). "One possible explanation for the high PTDSS1 dependency is that B cell lymphomas may distinguish the difference in the acyl-chain species of PS synthesized by PTDSS1 and PTDSS2." (PMID 38048228, 2024). "Therefore, the imbalance in the acyl-chain composition of PS in the condition of PTDSS1 inactivation may affect the efficiency of the exchange of PS/PIPs in B cell lymphomas." (PMID 38048228, 2024). "However, this is not the case for B cell lymphomas, which greatly required PS synthesis by PTDSS1, but not PTDSS2, for their growth in both in vitro culture and in vivo." (PMID 38048228, 2024).
developmental delays (1 paper, 2024). "Loss-of-function mutations in the PTDSS1 gene have been identified, correlating with some cases of developmental delay." (PMID 39409074, 2024). "Conversely, loss-of-function mutations in the PTDSS1 gene lead to developmental delays." (PMID 39409074, 2024).
esophageal squamous cell carcinoma (1 paper, 2026). Esophageal squamous cell carcinoma (ESCC) is a type of esophageal carcinoma (EC) that can affect any part of the esophagus, but is usually located in the upper or middle third. "PTDSS1 is an emerging oncogenic protein associated with poor survival rates across various cancer types, including esophageal squamous cell carcinoma (ESCC)." (PMID 42026035, 2026).
lymphoma (1 paper, 2024). A malignant (clonal) proliferation of B- lymphocytes or T- lymphocytes which involves the lymph nodes, bone marrow and/or extranodal sites. "PTDSS1 KO induced a similar phospholipid imbalance in SU-DHL-6 lymphoma cells." (PMID 38048228, 2024).
melanoma (1 paper, 2025). A malignant, usually aggressive tumor composed of atypical, neoplastic melanocytes. "Moreover, analysis of the public available ICT datasets revealed that high PTDSS1 RNA level and protein level in pretreatment human melanoma samples are correlated with poor patient survival and are associated with poor response to anti–PD-1 treatment, respectively." (PMID 40929270, 2025).
cancer (11 papers, 2013 to 2026). A tumor composed of atypical neoplastic, often pleomorphic cells that invade other tissues. "Although the elevated PA observed in some cancer cell lines also potentially enhances the association of Nir2/3 with the PM, it is still unclear how PTDSS1 inhibition activates the Nir2/3-mediated PI-cycle." (PMID 38048228, 2024). "Another study suggested that cancer cell populations with PTDSS2 deletion are highly susceptible to PTDSS1 inhibition." (PMID 38048228, 2024). "PTDSS1 inhibition causes a decrease in PE levels in a wide range of cancer cells." (PMID 38048228, 2024). "In this study, we used an in vivo CRISPR-Cas9 knockout screen in a murine cancer model to identify phosphatidylserine (PS) synthase 1 (Ptdss1) as an additional intrinsic regulator of tumor cell fitness under anti–PD-1–selective pressure." (PMID 40929270, 2025). "Pairing this with our finding that PTDSS1 is frequently amplified across diverse tumor types and associates with poor patient survival, these results indicates that PTDSS1 represents a broadly relevant target for developing novel cancer therapeutic strategies." (PMID 40929270, 2025). "Correlation analysis also showed that PTDSS1 expression is negatively correlated with cancer patient survival in various cancer types, suggesting a protumor role." (PMID 40929270, 2025). "A PTDSS1-specific inhibitor was recently developed based on synthetic lethal activity against cancer cells harboring a genetic deletion of PTDSS2, in which PTDSS1 inhibition causes profound loss of cellular PS and acute cell death." (PMID 38048228, 2024). "We screened a panel of human cancer cell lines for survival dependency on PS synthesis using a recently developed PTDSS1 inhibitor." (PMID 38048228, 2024). "A literature survey about significant biomarkers highlighted in survival analysis revealed that GNG11, CBX2, CDKN3, ARHGEF10, CLN8, SEC61G and PTDSS1 genes present similar survival and prognostic behaviors in the specified cancers." (PMID 37489460, 2023). "In this analysis to discover cancer subgroups, PTDSS1, MCM4 and PRKDC genes were identified as molecular drivers belonging to the same subgroup." (PMID 37489460, 2023). "Multivariate analysis indicated that transcriptional expression of predicted target genes (PDCD6, GNG5, PHF6, MAL2, SLC25A15 and PTDSS1) were significantly correlated with BLCA individual cancer stages and molecular subtypes." (PMID 35503998, 2022). "The inhibitors of PTDSS1 have shown anticancer potential in in vivo studies, suggesting they could be developed into effective cancer treatments." (PMID 39409074, 2024). "Two recent studies demonstrated that PTDSS1 is an attractive target for combating specific cancers." (PMID 38048228, 2024). "There have been some cancer-related reports addressing phosphatidylserine synthase 1 (PTDSS1)." (PMID 37489460, 2023). "Additionally, high transcriptional expression of PDCD6, GNG5, PHF6, MAL2, SLC25A15 and PTDSS1 were significantly correlated with BLCA individual cancer stages and molecular subtypes." (PMID 35503998, 2022). "The association of mRNA expression of predicted target genes (PDCD6, GNG5, PHF6, MAL2, SLC25A15, PTDSS1) with clinicopathological parameters of BLCA patients were analyzed by UALCAN, containing BLCA individual cancer stages and molecular subtypes." (PMID 35503998, 2022). "Nine out of 45 and 21 out of 84 genes for LUAD and LUSC, respectively, with high levels of differential expression based on cancer and healthy samples in TCGA database; the other genes, such as PKM and PTDSS1, have low levels of differential expression." (PMID 34137202, 2021). "ELOVL7, PTDSS1, POLR1D, TBC1D22A, CCNC and TCF25 are some of the interesting genes with cancer related functions identified from the DES analysis." (PMID 24088394, 2013).
cancer (continued). "Blocking PTDSS1 activity in these tumors deregulates phosphatidylinositol-4-monophosphate (PI4P) metabolism, affecting B cell receptor (BCR) function, ultimately leading to cancer cell apoptosis." (PMID 39409074, 2024). "Furthermore, we performed a pan-cancer analysis of predicted target genes (PDCD6, GNG5, PHF6, MAL2, SLC25A15 and PTDSS1) by using TIMER." (PMID 35503998, 2022). "In this regard, future studies should focus on addressing the expression status and activity of PS synthases PTDSS1 and PTDSS2 in different tumors, which might reveal important information in terms of mis-regulation of these enzymes in cancer." (PMID 26462157, 2015).
tumor (11 papers, 2013 to 2025). "Specifically, Ptdss1 deficiency increased tumor cell response to IFN-γ, immunogenicity, and sensitivity to CD8+ T cell–mediated killing." (PMID 40929270, 2025). "A key gene in the phospholipid metabolism is Ptdss1, which has been implicated to modulate tumor immune response." (PMID 40929270, 2025). "Ptdss1 deficiency in tumor cells also favored the development of a pro-inflammatory TME marked by an increase in cytotoxic CD8+ T cells." (PMID 40929270, 2025). "Specifically, Ptdss1-deficient tumor cells were more responsive to IFN-γ stimulation through the STAT1 signaling pathway, resulting in greater MHC-I surface expression, and, ultimately, enhanced CD8+ T cell–mediated cell killing in vitro." (PMID 40929270, 2025). "Loss of Ptdss1 in tumor cells also led to increased expression of MHC-I, enhanced cytotoxicity of CD8+ T cells, and increased frequency of an iNOS+ myeloid subset." (PMID 40929270, 2025). "Here, we found that Ptdss1 deficiency in tumor cells resulted in the up-regulation of genes involved in IFN response." (PMID 40929270, 2025). "Deletion of PTDSS1 in breast cancer cells reduced PS levels and tumor growth, which was associated with reduced abundance of macrophages, due to reduced proliferation, in tumors." (PMID 38573347, 2024). "Loss of PTDSS1 also increased the frequency of an iNOS+ (encoded by Nos2) myeloid cell cluster, which were typically observed in mice responding to ICT, and induction of this iNOS+ myeloid cell cluster by anti–PD-1 and PTDSS1 deficiency in tumor cells was synergistic." (PMID 40929270, 2025). "Together, these results suggest that loss of Ptdss1 in tumor cells shapes an inflammatory anti-TME." (PMID 40929270, 2025). "To determine whether loss of Ptdss1 led to any differences in cell proliferation and/or survival, we measured the cell growth rates in vitro by IncuCyte proliferation assay and in vivo by measuring tumor growth in immune-deficient NSG mice." (PMID 40929270, 2025). "Depletion of Ptdss1 in tumor cells increased expression of interferon-γ (IFN-γ)–regulated genes, including B2m, Cxcl9, Cxcl10, and Stat1, even in the absence of IFN-γ stimulation in vitro." (PMID 40929270, 2025). "In summary, we identified PTDSS1 as a regulator of tumor cell immunogenicity and antitumor immunity with both tumor cell–intrinsic and tumor cell–extrinsic roles." (PMID 40929270, 2025). "Together, these data suggest knocking down Ptdss1 in tumor cells sensitized tumors to anti–PD-1 treatment and this synergistic effect depends on an intact tumor immune microenvironment." (PMID 40929270, 2025). "PTDSS1 is a therapeutic target to enhance tumor immunogenicity and improve antitumor responses with immune checkpoint therapy." (PMID 40929270, 2025). "We found that both genetic and pharmacological inhibition of Ptdss1 in tumor cells significantly improved anti–PD-1 efficacy." (PMID 40929270, 2025). "Accordingly, potent and selective PTDSS1 inhibitors were developed, and their application in PTDSS2-deficient tumor models resulted in tumor regression." (PMID 38573347, 2024). "Another potential role played by PS during tumor immune responses is being a tumor antigen itself, which would be highly expressed due to increased PTDSS1-dependent production in tumors." (PMID 38573347, 2024). "PTDSS1-mediated phosphatidylserine signaling has been shown to be severely disrupted in metabolism of tumor cell and pathogenesis of autoimmune disorders." (PMID 35503998, 2022). "As KRAS has been shown to suppress STAT1 transcription, we hypothesize that PTDSS1 loss impairs RAS signaling, which in turn releases the suppression of STAT1 expression, enhancing tumor cell responsiveness to IFN-γ in a cell-intrinsic manner." (PMID 40929270, 2025). "Additionally, the protein expression of PTDSS1 in tumor tissues was stronger than that in normal tissues." (PMID 35503998, 2022). "The use of pharmacological compounds targeting PTDSS1 may be of interest for tumor therapy." (PMID 38573347, 2024).
tumor (continued). "PD-L1 and TIM3 ligands (LGALS9, PTDSS1, CEACAM1, and HMGB1) were identified on macrophages, DCs, and tumor cells." (PMID 40027748, 2025). "Our findings highlight a key role for Ptdss1 in regulating tumor cell immunogenicity and shaping TME, providing a strong rationale for combining PTDSS1 inhibition with PD-1 blockade to improve ICT efficacy." (PMID 40929270, 2025). "However decreasing PS levels in tumor cells by deleting PTDSS1 did affect macrophage activation but not efferocytosis." (PMID 38573347, 2024). "Disrupting PTDSS1 activity may therefore specifically affect tumor cells rather than untransformed cells that still express PTDSS2 to produce PS." (PMID 38573347, 2024). "Other TIM-3 ligands, carcinoembryonic antigen cell adhesion-related molecule 1 (CEACAM1) and phosphatidylserine synthase (PTDSS1, not shown), which are ubiquitously expressed by tumor cells, showed overall reduction likely due to oncolysis and remodeling of the tumor microenvironment." (PMID 35193929, 2022). "Western blot analysis showed that only the PTDSS2 protein level was stably elevated from both Brca1-MT mammary glands and tumor tissues of Brca1-MSK mice, but not PTDSS1." (PMID 35025764, 2022).
PTDSS1 also shares sentences with these, for which no sentence is quoted: lung adenocarcinoma (3 papers); cutis laxa (2); head and neck cancer (2); infection (2); sclerosing bone dysplasia (2); skeletal dysplasia (2); -Majewski syndrome (1); acute lymphoblastic leukemia (1); astroglioma (1); bladder cancer (1); breast tumor (1); Burkitt lymphoma (1); colorectal cancer (1); diffuse large B-cell lymphoma (1); Liberfarb syndrome (1); mantle cell lymphoma (1); multiple myeloma (1); pancreatic cancer (1); spondyloepimetaphyseal dysplasia (1).